FOSB (FosB proto-oncogene, AP-1 transcription factor subunit)
Diseases named in the same sentence as FOSB in open-access papers (continued):
Sharing a sentence is not in itself a finding about the gene and the disease.
acute leukemia (1 paper, 2014). A clonal (malignant) hematopoietic disorder with an acute onset, affecting the bone marrow and the peripheral blood. "Several (i.e. CEBPB, FOS and FOSB) were also described to be deregulated in the transition of CML blastic phase to an acute leukemia." (PMID 24517546, 2014). "As this step marks the transition to an acute leukemia, the overlapping genes (CEBPB, FOS, FOSB, IL8, S100A12, SOCS2) might be involved in the aggressiveness of MLL-AF9 myeloid leukemia blasts." (PMID 24517546, 2014).
amyotrophic lateral sclerosis (1 paper, 2009). Amyotrophic lateral sclerosis (ALS) is a neurodegenerative disease characterized by progressive muscular paralysis reflecting degeneration of motor neurons in the primary motor cortex, corticospinal tracts, brainstem and spinal cord. "In this case, 4 out of 5 genes from FOSB pathway were mapped to the 2 diseases: CDK5 and GRIA2 to amyotrophic lateral sclerosis and, FOSB and PPP1R1B to drug-induced dyskinesia." (PMID 19194489, 2009).
aneurysm (1 paper, 2025). Bulging or ballooning in an area of an artery secondary to arterial wall weakening. "While FOSB and RASSF2 have established roles in AAA literature 17, 18, our study represents the first report implicating FAP in aneurysm pathology." (PMID 40520892, 2025).
blood pressure (1 paper, 2023). "Can the increased FosB in the PVN explain the high blood pressure observed in GIH‐exposed rats?" (PMID 37642495, 2023).
Cerebral ischemia (1 paper, 2013). Restriction of arterial blood supply to the brain associated with insufficient oxygenation to support the metabolic requirements of the tissue. "Intriguingly, FBJ murine osteosarcoma viral oncogene homolog B (fosB) expression has been associated with stem cell and neural progenitor cells proliferation after cerebral ischemia in mammalian central nervous system." (PMID 25408907, 2013).
chronic myeloid leukemia (1 paper, 2022). "In chronic myeloid leukemia, FOSB could bind to the promoter of miR-22 and promotes its transcription, and knockdown of FOSB could inhibit the expression of miR-22." (PMID 35497876, 2022).
colitis (1 paper, 2023). Inflammation of the colon. "Dextran sulfate sodium (DSS)-induced colitis rats exhibited depressive-like behavior and increased expression of the immediate-early gene FosB/ΔFosB, inducible nitric oxide synthase (iNOS), and reactive microglia in the DRN during the resolution phase of experimental colitis." (PMID 36624089, 2023).
colon adenocarcinoma (1 paper, 2024). "Overexpression of FOSB decreased the transformation phenotype of gastric cancer cell lines in vitro, and Fosb expression was linked to elevated levels of cyclooxygenase-2 (COX2) in colon adenocarcinoma HCA-7 cells." (PMID 39264721, 2024).
colon carcinoma (1 paper, 2013). "As reported by these authors, JUN and FOSB are stress induced immediate early transcription factors which are components of AP-1 dimers, and these dimers have been found altered by ischemia in different tissues including prostate and colon cancer." (PMID 23308215, 2013).
coronary atherosclerosis (1 paper, 2025). Atherosclerosis of the coronary vasculature. "Furthermore, downregulated FOSB and MMP9 were found under the treatment of Insulin-like growth factor 1 that reduced reduces coronary atherosclerosis." (PMID 40486911, 2025).
dementia (1 paper, 2025). Loss of intellectual abilities interfering with an individual's social and occupational functions. "Significantly associated proteins at a false discovery rate (FDR) < 0.05 in both models 1 and 2 were CGREF1, MET, ALDH2, NECTIN2, APOC1, APOE and FOSB for HFRS, and CDK and POF1B for HFRS without dementia." (PMID 40764432, 2025).
diabetes (1 paper, 2021). "Here, we described chronic neuronal activity (i.e., FosB expression) in the spinal dorsal horn of segments L4–L5 and in the lateral part of PAG in our STZ diabetes model and found that PACAP treatment effectively prevented FosB activation in these centers." (PMID 34639032, 2021).
ductal carcinoma (1 paper, 2016). "A previous study indicated that FOSB is highly expressed in normal ductal mammary epithelium, but not in poorly differentiated ductal carcinoma." (PMID 27248170, 2016).
endometrial cancer (1 paper, 2022). Primary or metastatic malignant neoplasm involving the endometrium (mucous membrane that lines the endometrial cavity). "The upregulated hsa-mir-200a-b is associated with the decreased expression of the PTCH1, CCND2, PDGFRA, FOSB and ABL1 genes in endometrial cancer tissue while hsa-mir-429 is correlated with the decreased expression of the ALDH1A1 gene, besides some antibodies, PROTACs and inhibitory molecules." (PMID 36704357, 2022).
eosinophilia (1 paper, 2023). "Although FOSB fusions have not been found in cases of angiolymphoid hyperplasia with eosinophilia, the endothelial cells in this tumor are often positive for FOSB." (PMID 36983010, 2023). "Interestingly, angiolymphoid hyperplasia with an eosinophilia subtype (cutaneous epithelioid hemangioma) may be non-neoplastic as they lack FOS or FOSB gene rearrangement." (PMID 36983010, 2023).
estrogen-receptor positive breast cancer (1 paper, 2022). "Analyses of The Cancer Genome Atlas data indicated that higher ATF3, FOS, and FOSB expression levels correlated with low HSF1 levels in estrogen receptor-positive breast cancer, reflecting higher heat shock-induced expression of these genes in HSF1-deficient MCF7 cells observed in vitro." (PMID 36010586, 2022).
fatty liver disease (1 paper, 2024). A reversible condition wherein large vacuoles of triglyceride fat accumulate in liver cells via the process of steatosis. "Studies have shown that the expression of FOSB is significantly downregulated in patients with fatty liver disease." (PMID 38965537, 2024).
hepatitis B (1 paper, 2024). "The results showed an increased expression of FOSB in patients with hepatitis B, an increased expression of RNF43 in patients with hepatitis C, and an increased expression of RNF43 along with a decreased expression of RGCC in patients with AIH." (PMID 38965537, 2024). "We also examined FOSB, GPAT3, RGCC, and RNF43 expression in patients with hepatitis B, hepatitis C, and AIH." (PMID 38965537, 2024). "We also detected the expression of FOSB, GPAT3, RGCC, and RNF43 in the blood of patients with hepatitis B, hepatitis C and AIH." (PMID 38965537, 2024). "In addition, FOSB is reported to be related to hepatitis C, while RNF43 and GPAT3 are related to hepatitis B." (PMID 38965537, 2024).
infertile (1 paper, 2025). "Interestingly, our study observed elevated expression of FOS and FOSB in the SA group, while a previous study reported a decrease in expression of these genes among infertile men." (PMID 40938846, 2025).
lymphoma (1 paper, 2013). A malignant (clonal) proliferation of B- lymphocytes or T- lymphocytes which involves the lymph nodes, bone marrow and/or extranodal sites. "Median expression levels were invariably higher for AURKB, BCAT1, BIRC5, BUB1B, PBK and RACGAP1 and lower for FOSB, MAP3K1 and RIN3 by qPCR in lymphoma versus normal B cell samples in both species." (PMID 24130802, 2013).
meningioma (1 paper, 2017). A generally slow growing tumor attached to the dura mater. "In the canine genome, these lie in a contingent region of canine chromosome 1 and in our study, a number of meningiomas had increases in both SYNPO2 mRNA complementary to ZPF36 and FOSB." (PMID 29073243, 2017).
metastatic prostate carcinoma (1 paper, 2007). A carcinoma that arises from the prostate gland and has spread to other anatomic sites. "When applied to a novel set of genes differentially expressed between locally invasive and metastatic prostate cancer, Literature Lab identified a strong association between the pathway term "FOSB" and genes with increased expression in metastatic prostate cancer." (PMID 18088408, 2007).
morphine dependence (1 paper, 2012). Strong dependence, both physiological and emotional, upon morphine. "Given these facts, the following aim of this study was to identify the role of GC on FosB/ΔFosB expression in specific populations of the brain stress system during morphine dependence." (PMID 23185589, 2012). "This study examined the role of GC in regulation of FosB/ΔFosB in both hypothalamic and extrahypothalamic brain stress systems during morphine dependence." (PMID 23185589, 2012). "Studies have not yet examined the relationship between GC and morphine dependence-induced FosB/ΔFosB induction in the brain stress system." (PMID 23185589, 2012). "Supporting this hypothesis, our results show that FosB/ΔFosB-IR in the NAc(shell) and the CeA was attenuated in ADX animals, which might indicate a cross-talk between AP-1 transcription factors and GR during morphine dependence." (PMID 23185589, 2012).
non-alcoholic fatty liver disease (1 paper, 2024). "A recent microarray data analysis identified 4 non-alcoholic fatty liver disease (NAFLD)-related hub genes (DUSP1, NR4A1, FOSB, ZFP36) as diagnostic markers in chronic kidney disease patients with NAFLD." (PMID 38431286, 2024).
opiate dependence (1 paper, 2012). Disorders related or resulting from abuse or mis-use of opioids. "The present findings also indicate that FosB/ΔFosB may contribute to the GC-dependent changes on brain stress system plasticity during opiate dependence." (PMID 23185589, 2012).
osteoarthritis (1 paper, 2022). A noninflammatory degenerative joint disease occurring chiefly in older persons, characterized by degeneration of the articular cartilage, hypertrophy of bone at the margins and changes in the synovial membrane. "The classification model constructed by LASSO analysis showed that six genes including CDKN1A, FOSB, STMN2, SLC2A3, TAC, and SCRG1 can be used as biomarkers of osteoarthritis, and the SCRG1 gene shows importance in osteoarthritis." (PMID 35720295, 2022).
otitis media (1 paper, 2023). Inflammation of the anatomical structures of the middle ear, which is most often caused by an infectious process. "The fosB gene, which confers resistance to fosfomycin, was identified in one of our clinical isolates collected from an ear location with clinical manifestation as otitis media." (PMID 38075873, 2023).
pulmonary diseases (1 paper, 2021). "The FOSB expression varies in different pulmonary diseases and is an underlying biomarker to distinguish COPD-caused PAH and other types of PAH." (PMID 34880909, 2021).
renal carcinoma (1 paper, 2022). A carcinoma arising from the epithelium of the renal parenchyma or the renal pelvis. "To validate our results in clinical specimens, we used immunohistochemistry and semi-quantitative analyses, which showed that compared with adjacent tissues of renal cancer, FOSB and DUSP1 were down-regulated in the glomerulus of IgAN patients." (PMID 35910761, 2022).
retinal degeneration (1 paper, 2022). Degeneration of the retina. "From the transcriptomic analyses, we identified the apparent induction of FosB mRNA in the Lpcat1 KO retina during the progression of retinal degeneration." (PMID 35452679, 2022). "However, considering the role of FosB as a component of activator protein-1, a dimeric transcription factor involved in inflammation, angiogenesis, and apoptosis, our results suggest that Fosb inhibition may be involved in retinal degeneration in Lpcat1 KO mice." (PMID 35452679, 2022).
rosacea (1 paper, 2021). A chronic erythematous skin disorder that affects the face. "Our results were consistent with the hypothesis that AP1 TFs (FOS, FOSB, JUN and JUND) were downregulated in rosacea lesions." (PMID 34290700, 2021).
sarcoma (1 paper, 2025). A usually aggressive malignant neoplasm of the soft tissue or bone. "The detection of ACTB::FOSB fusion is consistent with PMH’s diagnosis and supports its differentiation from other sarcomas, with both diagnostic and potential therapeutic implications." (PMID 40277775, 2025).
scrub typhus (1 paper, 2011). Scrub typhus is a rare dust mite-borne infectious disease caused by the Orientia tsutsugamushi bacterium and characterized clinically by an eruptive fever which is potentially serious. "The transcriptional signature of patients with scrub typhus included the differential expression of the CBLB, LOC642161, CD8A, CD8B1 and FOSB genes, when compared to healthy controls and patients with other infectious diseases." (PMID 21610853, 2011).
staphylococcal infection (1 paper, 2023). An infection caused by Staphylococcus. "The high prevalence of some antibiotic genes in this study, such as fosB, in MRSA isolates raises concerns regarding the potential compromise of fosfomycin as a last-resort therapy for staphylococcal infections." (PMID 38282615, 2023).
steatosis (1 paper, 2020). Increased lipid within the cytoplasm of cells. "Of the top-ranked 10 genes, two genes (CYP7A1 and PEG10) were significantly up-regulated in both steatosis and NASH patients, while eight genes (FOSB, FOS, IL6, GADD45G, MYC, SLITRK3, JUNB, and IGFBP2) were significantly down-regulated." (PMID 33324350, 2020).
synovial sarcoma (1 paper, 2021). "Here, we found that TP4 also disrupts calcium homeostasis in synovial sarcoma cells; however, the activation status of FOSB in TP4-treated synovial sarcoma cells remains unclear." (PMID 33562681, 2021).
tumor (86 papers, 2005 to 2026). "Differential gene expression highlighted immune regulation pathways and transcriptional networks centered on JUN, JUNB, and FOSB, linked to immune suppression and tumor progression." (PMID 42004296, 2025). "Association of the expressions of SRC, JUNB, FOSB and PD-L1 as well as clinicopathological characteristics in tumor samples of KRAS-mutant NSCLC patients." (PMID 40599804, 2025). "RNA-seq identified robust induction of xenobiotic metabolism (CYP1A1, CYP1B1), oxidative/metabolic stress mediators (GDF15, TIPARP), and tumour-associated genes (FOSB, VGF), alongside repression of tumour suppressors (FAT1, LINC00472)." (PMID 41600570, 2025). "Association of the expressions of SRC, JUNB and FOSB as well as PD-L1 expression in tumor samples of KRAS-mutant NSCLC patients." (PMID 40599804, 2025). "Top DGEs included the proto-oncogenes, FOS and FOSB, which were identified as two of the most upregulated features in tumor-infiltrating B cells." (PMID 39932553, 2025). "The immunohistochemistry images revealed that SRC was located mainly in the cytoplasm of the tumor cells; JUNB and FOSB were located mainly in the cell nucleus; and PD-L1 was located mainly in the cytoplasm and nucleus of the tumor cells." (PMID 40599804, 2025). "Tumor biology studies have indicated that FOSB-mediated transcriptional activation of the matrix metalloproteinase MMP-2 is involved in the invasion and metastasis in NSCLC driven by the pro-survival protein Bcl-2." (PMID 39164746, 2024). "Immunohistochemical (IHC) staining showed that the tumor cells were diffusely and strongly positive for FOSB, pan-cytokeratin (AE1/AE3), CD31, and ERG." (PMID 38337858, 2024). "Tumor cells from the IgG and PD-1 groups were mainly clustered in the invasive and migrative branches (H3F3B+ and FOSB+ tumor cells), while cells from the SMI group were mainly clustered in the CSCs and EMT branches (NEAT1+ and S100A4+ tumor cells)." (PMID 37430270, 2023). "As for FOSB, it has been documented as a fundamental factor supporting migration and invasion of tumor cells." (PMID 37173692, 2023). "Next, another two trajectory branches, EMT-induced XIST+ tumor cells and invasive and migrative FOSB+ tumor cells, were separated after S100A4+ tumor cells." (PMID 37430270, 2023). "Its higher expression was related to better RFS in TNBC and Her2‐ BC based on Oncomine and TCGA datasets, and increased TNBC cell proliferation in the FOSB knockout model conversely indicated its ability of tumor inhibition." (PMID 35037412, 2022). "The results indicated that silencing of SETDB1 limited tumor cell proliferation and the infiltration of tumor cells by T cells via FOSB/miR-22/BATF3/PD-L1 axis and consequently arresting tumor cell immune evasion." (PMID 35497876, 2022). "The results showed that the expression of ANGPT2, VCAN, and FosB in tumor tissue were higher than normal tissue." (PMID 36569220, 2022).